DRAIC (downregulated RNA in cancer, inhibitor of cell invasion and migration)
Diseases named in the same sentence as DRAIC in open-access papers (continued):
Sharing a sentence is not in itself a finding about the gene and the disease.
tumor (22 papers, 2015 to 2025). "DRAIC(down-regulated RNA in androgen independent cells, LOC145837) and PCAT29 (PC-associated transcript 29), both locus on human chromosome 15q23, were reported as novel tumor suppressive gene in 2015." (PMID 30037351, 2018). "A tumor-suppressive long-noncoding RNA (lncRNA) DRAIC (downregulated RNAin cancers) inhibits NF-κB activity and physically interacts with IKKα, a kinase component of the IKK complex, in several cancer types." (PMID 40320073, 2025). "The A + B DRAIC fragment alone significantly decreased tumor cell invasion, and removing A + B from 705 to 950 completely abolished this effect, demonstrating that A + B is sufficient and necessary for DRAIC to inhibit tumor cell invasion." (PMID 40320073, 2025). "We demonstrated that the same 204-base region of DRAIC exerts its tumor suppressive function and interrupts the IKK complex, which is the key upstream regulator of the NF-κB signaling pathway." (PMID 40320073, 2025). "Because of the great diversity of which isoform of DRAIC is dominant in a given tumor, this information will be critical for determining the function of DRAIC in clinical specimens." (PMID 40320073, 2025). "DRAIC expression was comprehensively analyzed using tissue microarrays containing 89 normal and 155 tumor tissue samples." (PMID 38075206, 2024). "Subsequent studies have demonstrated that DRAIC is dysregulated in various malignancies and exhibits a tumor-suppressive or pro-oncogenic function." (PMID 38075206, 2024). "Based on the results using the FFPE cell block samples and xenograft tissues, we performed the RNAscope CISH on the TMAs to comprehensively evaluate the expression pattern of DRAIC in normal and tumor tissues." (PMID 38075206, 2024). "Many of these miRNAs are characterised as tumour promoters, implicating DRAIC as suppressive tumour lncRNA." (PMID 39410631, 2024). "lncRNA DRAIC repressed cell proliferation, migration, invasion, and in vivo xenograft tumor growth, as well as induced cell autophagy in U251, A172, and U87 cells." (PMID 35992823, 2022). "Several studies have shown that lncRNA DRAIC is dysregulated in PCa LNCaP and C4-2B cells as well as in 7 PCa tumor biopsies by androgens in a dose and time-dependent manner." (PMID 35992823, 2022). "The lncRNA DRAIC gene, which is located on human chromosome 15q23, was reported as a novel tumor regulator in several cancers recently, but it seemed to exhibit different biological effects in cancer cells from different sources." (PMID 32351584, 2020). "In this study, we included expression analysis of DRAIC in 828 tumor samples and 105 normal breast samples from TCGA." (PMID 30544991, 2018). "In our current study, we only focused on the interaction of DRAIC with IKKα, and there could be other interesting proteins that interact with DRAIC (or even A + B) to contribute to the tumor-suppressive function of DRAIC." (PMID 40320073, 2025). "In tumor tissues (n = 155), DRAIC was moderately to highly expressed in some instances." (PMID 38075206, 2024). "In contrast, other studies suggest that DRAIC might act as a tumour inhibitor; however, the exact mechanisms remain to be elucidated." (PMID 39410631, 2024). "In addition, lncRNA DRAIC stimulated tumor progression through the promotion of cell proliferation, migration, and invasion, as well as the inhibition of cell autophagy and apoptosis in SKBR3, MCF-7 and MDA-MB-231 cells." (PMID 35992823, 2022). "Moreover, lncRNA DRAIC expression was shown to reflect the sensitivity of tumor cells to chemotherapy or radiotherapy." (PMID 35992823, 2022). "Moreover, lncRNA DRAIC was considered to be a tumor suppressor by preventing the transformation of cuboidal epithelial cells to fibroblast-like morphology as well as cell migration and invasion." (PMID 35992823, 2022). "The expression of DRAIC was investigated in 828 tumor tissues and 105 normal breast tissues." (PMID 30544991, 2018).
tumor (continued). "DRAIC expression correlated with tumor stage and lymph node metastasis." (PMID 30544991, 2018). "Similar to DRAIC, lncRNA PCAT29 acts as a tumor suppressor via modulation of AR." (PMID 27686732, 2016). "Moreover, the negative correlation between DRAIC expression and tumour stage in LUAD supports our hypothesis, that DRAIC might play a tumour-inhibitor role in LUAD, as higher DRAIC expression was observed in early-stage compared to late-stage LUAD." (PMID 39410631, 2024). "Firstly, lower expression of DRAIC was found in GC tissues and cell lines, and indicated the higher lymph node metastasis rate of GC patients, which indicated that DRAIC may play a role as a potential tumor suppressor gene in GC." (PMID 32351584, 2020). "In addition, high expression of nuclear factor kappa-B (NF-κb) was found in the tumor tissues with inferior DRAIC, and vitro and vivo studies verified that DRAIC could inhibit activation of NF-κb and prostate cancer progressions via binding to subunits of the IκB kinase (IKK) complex." (PMID 32351584, 2020).
cancer (16 papers, 2015 to 2025). A tumor composed of atypical neoplastic, often pleomorphic cells that invade other tissues. "In general, lncRNA DRAIC was proved to be a potential diagnostic and prognosis biomarker, together with a treatment target for human cancers." (PMID 35992823, 2022). "For this reason, the expression of the DRAIC/PCAT29 locus is associated with a good cancer prognosis." (PMID 29755696, 2018). "Therefore, the A + B hairpin within DRAIC represents a promising therapeutic agent, offering new avenues for the development of cancer treatments aimed at curbing the malignancy associated with hyperactive NF-κB signaling." (PMID 40320073, 2025). "The positive effects that are associated with DRAIC are not limited to one type of cancer; DRAIC expression also correlates with a good prognosis in bladder cancer, lung and stomach adenocarcinomas, renal and hepatocellular carcinomas, melanoma and low-grade glioma." (PMID 29755696, 2018). "In conclusion, our study identifies a critical secondary structure within DRAIC that specifically interacts with IKKα to inhibit NF-κB signaling and suppress cancer cell aggressiveness." (PMID 40320073, 2025). "Based on the DRAIC expression analyzed using the Cancer Cell Line Encyclopedia (CCLE) dataset, we selected three human cancer cell lines: VMRC-LCD, 22Rv1, and PC3 cells." (PMID 38075206, 2024). "Take together, DRAIC was involved in the multiple biological process of cancers through interaction with diverse molecules." (PMID 35992823, 2022). "The lncRNA DRAIC, a newly discovered lncRNA, has been found to be abnormally expressed in a variety of diseases, particularly cancer." (PMID 35992823, 2022). "Downregulated RNA in cancer (DRAIC, Gene ID: 145837) is a lncRNA whose coding gene is located on the chromatin of 15q23, which is abnormally expressed in a variety of malignant tumors." (PMID 34471485, 2021). "Based on the differential expression of DRAIC in GC and NC tissues and its potential role in several malignant tumors, we decided to explore the relationship between DRAIC/NFRKB and malignant phenotype of GC cells." (PMID 32351584, 2020). "We showed that DRAIC expression was significantly higher in cancer tissues than normal tissues, consistent with a previous report." (PMID 30544991, 2018). "By defining a very small specific interaction region of DRAIC and its target and finding that this same region is critical for inhibiting NF-κB and key cancer pathways, we strongly suggest that NF-κB inhibition is the key pathway by which DRAIC exerts its anticancer function." (PMID 40320073, 2025). "Additionally, DRAIC is found to be downregulated in several cancers, including gastric, lung, and liver." (PMID 39410631, 2024). "We first evaluated the expression of DRAIC in human cancer cell lines." (PMID 38075206, 2024). "The GO terms related to NE were enriched by knockdown, which suggests that DRAIC might be involved in the characteristics of cancer cells with NE-differentiation, although the molecular mechanisms are unknown." (PMID 38075206, 2024). "Because DRAIC induces or represses cellular invasion, depending on cancer cell types, we should analyze the cellular phenotypes in vitro and in vivo using various NE-differentiated cancer cells." (PMID 38075206, 2024). "Aberrant expression of DRAIC was also related to other types of cancers." (PMID 30544991, 2018). "Finally, DRAIC expression predicts good outcome in multiple different cancer types, suggesting that it has potential as a therapeutic RNA, but here again, we need to define smaller functional modules of the RNA, because it is easier to deliver small RNAs to tumors." (PMID 40320073, 2025). "In the neuroendocrine-differentiated cancer cell line VMRC-LCD, CISH revealed a diffuse localization of DRAIC in the cytoplasm as well as specific accumulation in the nuclear compartment." (PMID 38075206, 2024).
cancer (continued). "We have discovered that the anti-invasion, -migration, and -clonogenicity function of DRAIC, and the interaction with and inhibition of IKK map to the same small part of the RNA, strongly suggesting that the anti-cancer cell functions are mediated by IKK inhibition." (PMID 40320073, 2025). "It is important to first understand which small structural modules of DRAIC are required for interaction with IKKα, NF-κB inhibition, and suppression of cancer phenotypes, before we can determine which splice isoforms of DRAIC are functional or not." (PMID 40320073, 2025). "It was found that oeNFRKB could alleviate the anti-cancer effect induced by DRAIC in HGC-27 and MKN45 cells, suggesting that DRAIC plays an anti-cancer role by suppressing NFRKB." (PMID 32351584, 2020). "Finally, NF-κB has a critical role not only in cancer biology but also in immunology, and we have not addressed whether DRAIC, A + B, or splice isoforms of DRAIC play an important role in the regulation of inflammation and the immune response." (PMID 40320073, 2025). "However, while DRAIC knockdown in MCF7 cells inhibited E2-regulated gene expression, the expression of DRAIC itself was also inhibited by E2 treatment and it was speculated that DRAIC may be important for both E2-dependent and the basal growth of cancer cells." (PMID 30544991, 2018). "While DRAIC knockdown did not affect VMRC-LCD cellular viability and invasive ability, gene expression related to the neuroendocrine and cancer-related pathways was altered." (PMID 38075206, 2024).
DRAIC also shares sentences with these, for which no sentence is quoted: prostate tumors (3 papers); bladder cancer (2); glioblastoma multiforme (2); lung fibrosis (2); non-small cell lung carcinoma (2); omphalocele (2); adenocarcinoma (1); bipolar disorder (1); colon adenocarcinoma (1); Hirschsprung disease (1); invasive ductal carcinoma of the breast (1); lung squamous cell carcinoma (1); metastatic prostate carcinoma (1); neuroendocrine carcinoma (1); pancreas cancers (1); rectum adenocarcinoma (1); small cell lung carcinoma (1); squamous cell carcinoma (1); triple-negative breast carcinoma (1).